Y_RNA (Y RNA )
Gene: Miscellaneous RNA gene on chromosome 5 (32,134,738 to 32,134,834, forward strand). Ensembl gene ENSG00000200065.
Homologues: Paralogues in human: Y_RNA (82% identical), Y_RNA (81% identical), Y_RNA (79% identical), RNY3 (78% identical), Y_RNA (78% identical), RNY3P1 (77% identical), Y_RNA (77% identical), Y_RNA (76% identical), RNY3P16 (75% identical), RNY3P2 (75% identical), RNY3P5 (75% identical), Y_RNA (75% identical), and 89 more.